LINC03090 (long independently transcribed non-coding RNA 3090)
Gene: Long non-coding RNA gene on chromosome 8 (101,125,016 to 101,153,675, forward strand). Ensembl gene ENSG00000253355.
Diseases named in the same sentence as LINC03090 in open-access papers:
LINC03090 is named in the same sentence as 1 disease in open-access papers, as found by Europe PMC text mining. Sharing a sentence is not in itself a finding about the gene and the disease. The quoted sentences say what the papers report.
bipolar disorder (1 paper, 2025). A disorder of the brain that causes unusual shifts in mood, energy, activity levels and the ability to carry out day-to-day tasks. "Therefore, examining LINC03091 and LINC03090 in bipolar disorder allows us to examine whether their dysregulation represents a common pathway across different psychiatric conditions or is specific to specific diagnostic boundaries." (PMID 41298728, 2025).